FAM90A24 (family with sequence similarity 90 member A24)
Synonyms: FAM90A24P
Tractability: No criterion of Open Targets' tractability assessment is met for any kind of drug.
Gene: Protein-coding gene on chromosome 8 (8,019,988 to 8,022,998, reverse strand). Ensembl gene ENSG00000215354.
Subcellular location (Human Protein Atlas): Nucleoplasm; Nucleoli
Homologues: Orthologues: mouse Fam90a1b (28% identical), mouse Fam90a1a (27% identical), rat Fam90a1l1 (26% identical). Paralogues in human: FAM90A13 (99% identical), FAM90A15 (99% identical), FAM90A23 (99% identical), FAM90A14 (98% identical), FAM90A22 (98% identical), FAM90A5 (98% identical), FAM90A16 (98% identical), FAM90A17 (98% identical), FAM90A12 (98% identical), FAM90A3 (98% identical), FAM90A8 (98% identical), FAM90A9 (98% identical), and 9 more.
Diseases named in the same sentence as FAM90A24 in open-access papers:
FAM90A24 is named in the same sentence as 2 diseases in open-access papers, as found by Europe PMC text mining. Sharing a sentence is not in itself a finding about the gene and the disease.
FAM90A24 shares sentences with these, for which no sentence is quoted: cutaneous melanoma (1 paper); endocervical carcinoma (1).